ELF3 (E74 like ETS transcription factor 3)
Diseases named in the same sentence as ELF3 in open-access papers (continued):
Sharing a sentence is not in itself a finding about the gene and the disease.
cancer (continued). "To examine if ELF3, EHF and TGIF1 levels are important in human cancers, we measured mRNA expression of these in LUAD tissues along with their paired adjacent peritumoral tissues." (PMID 33070167, 2020). "We leveraged gene expression profiles of 13 tissues to construct ELF3 protein–protein interaction (PPI) networks, and assessed their disruption in a pan-cancer analysis." (PMID 31780666, 2019). "A panel of eight cancer driver genes (CCNE1, TPX2, ELF3, FANCL, JAK2, GSK3B, CEP76, and SYK) were differentially expressed in recurrent TNBCs, and were also overexpressed in TCGA and METABRIC." (PMID 30665374, 2019). "First, we targeted the following loci given the initial observation from TCGA: five imprinted domains (PEG3, H19/IGF2, DLK1/GTL2, MEST, GNAS) and four cancer genes (APC, MLL3, MGMT, ELF3)." (PMID 26338779, 2015). "Although mild expressions were demonstrated in total cancer cell cluster C1 and C8 in non‐recurrent group, the CLDN4 expression along with ELF3, TACSTD2 and EpCAM could only be seen in recurrent cells of total C1." (PMID 38629624, 2024). "ELF3, which is predicted to drive the expression of highly expressed ID genes ANXA3, TGFB2, and duct marker KRT8, has been shown to drive ligand-independent transactivation of CTNNB1 in cancer models." (PMID 36540608, 2022). "Many cancer sections either showed no ELF3 staining, or showed high ELF3 expression in non‐cancerous, AMACR‐negative glands, regardless of Gleason grade." (PMID 35472129, 2022). "Similarly, we detected binding motifs for ELF3, KLF, and JUN in the cancer-enriched constituent enhancers of SE14." (PMID 35869079, 2022). "Compared to ELF3, mutations in EHF are relatively rare in human cancers and are not frequently deposited in public datasets." (PMID 33712555, 2021). "Furthermore, we investigated and analyzed the expression of ELF3 and IRF6 in GC tissues from TCGA by using the bioinformatics tool GEPIA, a web server for cancer and normal gene expression profiling and interactive analyses." (PMID 31019894, 2019). "E74-like ETS tanscription factor 3 (ELF3) is a member of the epithelial-specific subfamily of ETS transcription factors, which plays a role in a variety of pathophysiologic processes including cancer and immune system disorders." (PMID 29523781, 2018). "Therefore, EHF, rather than ELF3, would be very involved in cancer progression in HNSCC." (PMID 33712555, 2021). "In terms of targeting the proliferation controlled by ELF3 therapeutically, our data would suggest extreme caution as compensatory activation of other ETS family members, most notably ETV5, which is a known oncogene in PCa, could result in cancer progression rather than regression." (PMID 35472129, 2022).
infection (13 papers, 2011 to 2025). The state of being infected such as from the introduction of a foreign agent such as serum, vaccine, antigenic substance or organism. "Gene expression studies in zebrafish indicate that elf3 is upregulated by microbiota colonization in intestinal enterocytes and goblet cells, and is also upregulated in response to pathogenic infections (28, –, 30)." (PMID 41147741, 2025). "Mutation of elf3 led to immune-related pathologies such as inflammation and infection of the swim bladder, granuloma formation, and reduced survival in adulthood." (PMID 41147741, 2025). "Additional studies are needed to assess the effects of elf3 mutation on the microbiome of larval zebrafish and adult tissues that may contribute to infection, such as the intestine and swim bladder." (PMID 41147741, 2025). "Alternatively, or in concert, reduced function of the pneumatic duct in elf3 mutants could cause or impair swim bladder buoyancy regulation and subsequently render the duct and swim bladder susceptible to inflammation and infection." (PMID 41147741, 2025). "ELF3 was also downregulated, and one of its gene ontogeny biological processes terms was inflammatory response to infection (GO:0,006,954)." (PMID 34650121, 2021). "Our further finding that Myb and Elf3 undergo a particular spike in expression in the idiopathic preterm labor model associated with PR function loss, but not in the infection-simulating model, suggests that the corresponding proteins may be involved in particular pathways in laboring SMCs." (PMID 36595497, 2023). "We could identify reference genes that are suitable for expression profiling during the infection process in planta and combined with the germ tube stage: CytB/PDK or CytB/GAPDH and Elf3/RPS9 or PKD/GAPDH are suitable reference gene combinations." (PMID 26404265, 2015). "Bacterial titres were again significantly lower in Col-0 plants when infected at CT26 compared to CT42, while no differential response to time of infection was observed in either elf3-1 or CCA1-ox." (PMID 22066021, 2011).
adenocarcinoma (6 papers, 2014 to 2025). A common cancer characterized by the presence of malignant glandular cells. "In adenocarcinoma variations included somatic mutations in ELF3 (13%) and CBFB (8%) genes." (PMID 25220666, 2014). "In this study, we have comprehensively analyzed 1835 human clinical samples of NSCLC and identify a disparate ELF3 expression pattern in the adenocarcinoma (LUAD) and squamous cell carcinoma (LUSC) histological subtypes." (PMID 31780666, 2019).
inflammation (2 papers, 2014 to 2023). Aberrant reaction of the microcirculation characterized by movement of fluid and leukocytes from the blood into extravascular tissues. "The one de novo motif identified for WT lost VELs closely matched the known binding motif for ELF3, a member of the ETS family that is a known mediator of vascular inflammation." (PMID 36817228, 2023).
head and neck tumors (1 paper, 2022). "ELF3 is highly expressed in head and neck tumors and upregulates the epidermal growth factor receptor (EGFR) and human epidermal growth factor receptor 2 (HER2) to attenuate the antiproliferative effects of EGFR/HER2 tyrosine kinase inhibitors (lapatinib and afatinib)." (PMID 35845594, 2022).
immune dysfunction (1 paper, 2025). "ELF3 and ATF4 were identified as key regulators linking butyrate metabolism to PD-1 expression, providing a molecular bridge between microbiome and immune dysfunction." (PMID 41438381, 2025).
ELF3 also shares sentences with these, for which no sentence is quoted: ductal carcinoma in situ (3 papers); rectum adenocarcinoma (3); stomach adenocarcinoma (3); glioblastoma (2); glioma (2); hyperlipidemia (2); oral squamous cell carcinoma (2); Papillary Thyroid Cancer (2); sarcoma (2); adenomyosis (1); astrocytoma (1); bacterial infection (1); cardia cancer (1); cervical squamous cell carcinoma (1); cholangiocarcinoma (1); cystic fibrosis (1); diabetes mellitus type 2 (1); diabetic nephropathy (1); endocervical adenocarcinoma (1); epithelial ovarian tumor (1); esophageal cancer (1); fatty liver disease (1); glomerulosclerosis (1); Granuloma (1); head and neck cancer (1); hematologic diseases (1); Hepatic steatosis (1); Insulin resistance (1); intrahepatic cholangiocarcinoma (1); ischemic stroke (1).
A further 27 diseases each share a sentence with ELF3 in 1 paper.